RND3 (Rho family GTPase 3)
Diseases named in the same sentence as RND3 in open-access papers (continued):
Sharing a sentence is not in itself a finding about the gene and the disease.
diabetic cardiomyopathy (2 papers, 2022 to 2025). Diabetic cardiomyopathy is a disorder of the heart muscle in people with diabetes. "In conclusion, findings of this study indicate a novel mechanism for alleviating diabetic cardiomyopathy and highlight the therapeutic promises of targeting Rnd3 in the management of DCM." (PMID 36438502, 2022). "Here we tested the role of Rnd3 in cardiomyocyte senescence and diabetic cardiomyopathy (DCM)." (PMID 40025898, 2025).
heart failure (2 papers, 2021 to 2022). Inability of the heart to pump blood at an adequate rate to meet tissue metabolic requirements. "Cardiac Rnd3 mRNA expression was reported significantly lower in human heart failure, according to a microarray screening study (Profile GDS651/212724_at/RND3 in NCBI GEO profiles)." (PMID 36438502, 2022).
liver cancer (2 papers, 2024). An epithelial or non-epithelial malignant neoplasm that arises from the liver. "Here, we reported that HCC cells are susceptible to form entosis after Rnd3 downregulation in cultured liver cancer cell lines and in xenografts in mice." (PMID 38218945, 2024). "However, in liver cancer cells, the loss of Rnd3 is important in both the inner and outer cells, as a maximum of entosis was found when Rnd3 expression is decreased in both the inner and the outer cells." (PMID 38218945, 2024). "Moreover, Rnd3 loss was associated with liver cancer cell proliferation, invasion, chemoresistance, and senescence." (PMID 38218945, 2024). "KIAA1429 increases the m6A methylation in 3′-UTR of the RND3 mRNA and decreases its stability via m6A reader YTHDC1 (YTH N6-methyladenosine RNA binding protein C1), and then down-regulates the RND3 expression level in liver cancer." (PMID 39456252, 2024). "To examine whether the silencing of Rnd3 may trigger this mechanism, we first analyzed Rnd3 expression in liver cancer and MCF-7 cells." (PMID 38218945, 2024). "Thus, the Rnd3 role appears to be different in breast and liver cancers." (PMID 38218945, 2024). "While working on the role of Rnd3 in HCC, we observed CIC structures, prompting us to study this phenomenon in liver cancer cells." (PMID 38218945, 2024).
lung adenocarcinoma (2 papers, 2014 to 2026). A carcinoma that arises from the lung and is characterized by the presence of malignant glandular epithelial cells. "Here, we show lung adenocarcinoma patients expressing low levels of Rnd3 have significantly higher survival rates." (PMID 41735013, 2026). "To gain mechanistic insight into this correlation, we knocked down Rnd3 in lung adenocarcinoma A549 and H460 cell lines and patient-derived lung-to-brain metastasis (PDLBM) cell lines as a proxy for advanced disease." (PMID 41735013, 2026). "Depletion of Rnd3 expression decreases cell invasion and migration, two hallmarks of metastasis, independently of RhoA-ROCK1 signaling in both lung adenocarcinoma and PDLBM cell lines, indicating the involvement of a novel pathway." (PMID 41735013, 2026).
multiple myeloma (2 papers, 2020 to 2023). "The lentiviral particles were used to transduce two different multiple myeloma cell lines, RPMI 8226 and JJN3, and downregulate Rnd3 expression." (PMID 37143063, 2023). "The microarray data also pointed to a significant upregulation of two primary MAFB target genes, i.e., RND3 and MYO5A, which were known to be upregulated in multiple myeloma plasma cells." (PMID 32178359, 2020).
neuroblastoma (2 papers, 2010 to 2012). Neuroblastoma (NB) is the most common solid, extracranial childhood tumor. "For example RhoU, RhoBTB1 and especially Rnd2 are expressed in neuroblastoma, while Rnd3 is expressed in HeLa and neuroblastoma." (PMID 22916134, 2012). "This study started with a proteomic approach to identify Rnd3 targets in mES E14 cells and revealed Syx to be relatively abundant in mES, neuroblastomas and Hela cells." (PMID 20811643, 2010). "The affinity purified anti-Rnd3 and Syx antibodies (see methods section) detected both these proteins in lysates of human HeLa, mouse neuroblastoma NIE-115 and mES E14 cells, though the levels of Rnd3 protein is much lower in NIE115." (PMID 20811643, 2010).
preeclampsia (2 papers, 2022 to 2023). Preeclampsia is a hypertensive disorder of pregnancy that is characterized by new-onset hypertension with proteinuria presenting after 20 weeks of gestation, and depending on mild or severe forms may initially present with severe headache, visual disturbances, and hyperreflexia. "While TUG1 downregulation boosted the expression of the enhancer of zeste homolog 2 (EZH2) and decreased the levels of the Rho family GTPase 3 (RND3) in Preeclampsia, it prevented remodeling of the uterine spiral artery." (PMID 37745705, 2023).
skin cancer (2 papers, 2015). "Given the fact that the decrease in RND3 expression levels was detected in both GBM and skin cancer, an alternative or additional mechanism of transcriptional regulation of RND3 may exist." (PMID 26108681, 2015).
adenoma (1 paper, 2019). A neoplasm arising from the epithelium. "All investigated and expressed target genes, CDKN1B, PTPN13, RND3, SOX2 and ZEB2, were down-regulated in adenoma compared to normal mucosa of CRC N0, except ONECUT2 and TGFB2, which were up-regulated." (PMID 31623346, 2019). "In contrast to adenoma, investigated target genes CDKN1B, PTPN13, RND3, SOX2 and ZEB2 were up-regulated in CRC N0, except ONECUT2 and TGFB2, which were down-regulated." (PMID 31623346, 2019). "The majority of target genes (CDKN1B, PTPN13, RND3, SOX2 and ZEB2) were down-regulated in adenoma compared to normal mucosa." (PMID 31623346, 2019). "In adenomas, differential expression in comparison with CRC N0 was also observed for ZEB2 (p = 0.034) and SOX2 (p = 0.046), and in comparison with CRC N+, ONECUT2 (p = 0.006) and RND3 (p < 0.001)." (PMID 31623346, 2019).
cardiac ischemia (1 paper, 2024). "Inhibition of miR-205 expression promotes Rho family GTPase 3 activity in cardiac ischemia/reperfusion injury, regulating the function of the heart and mitochondria and, thus, reducing oxidative stress and apoptosis." (PMID 38671899, 2024).
cocaine abuse (1 paper, 2023). Disorders related or resulting from use of cocaine. "Considering the role of the Rnd subfamily in actin cytoskeleton modulation and synaptic plasticity, cocaine regulation of Rnd3 gene expression suggests that Rnd3 is involved in the growth of neurites and modification of dendritic branches induced by cocaine abuse." (PMID 37063367, 2023).
congenital hydrocephalus (1 paper, 2018). Hydrocephalus that is present at birth. "In addition, loss of RND3 (3.21-fold higher in B6, but only differentially expressed in the nm1054 comparison), which regulates cytoskeletal organization and cell adhesion, results in congenital hydrocephalus in mice due to altered Notch signaling." (PMID 30190587, 2018).
dilated cardiomyopathy (1 paper, 2019). Cardiomyopathy which is characterized by dilation and contractile dysfunction of the left and right ventricles. "Moreover, mice with genetic deletion of Rnd3 developed dilated cardiomyopathy after aortic banding, whereas cardioprotective effects were seen in Rnd3 transgenic mice." (PMID 30895179, 2019).
esophageal squamous cell carcinoma (1 paper, 2014). Esophageal squamous cell carcinoma (ESCC) is a type of esophageal carcinoma (EC) that can affect any part of the esophagus, but is usually located in the upper or middle third. "While down-regulation of Rnd3 was observation in human liver tumor tissue and human esophageal squamous cell carcinoma tissues compared to the adjacent normal tissues respectively." (PMID 25372032, 2014).
fibrosis (1 paper, 2022). the formation of excess fibrous connective tissue in an organ or tissue in a reparative or reactive process. "Our data demonstrated improvement in interstitial and perivascular fibrosis, myocardial structure and function upon Rnd3 over-expression." (PMID 36438502, 2022).
Miscarriage (1 paper, 2020). A pregnancy that ends at a stage in which the fetus is incapable of surviving on its own, defined as the spontaneous loss of a fetus before the 22th week of pregnancy. "In the present study, we found that RND3 expression was significantly increased in trophoblasts from the villous tissues of patients with recurrent miscarriage (RM)." (PMID 32232044, 2020).
myocardial infarction (1 paper, 2023). Gross necrosis of the myocardium, as a result of interruption of the blood supply to the area, as in coronary thrombosis. "Rnd3 has shown overt protective effects in a wide range of cardiovascular diseases, including myocardial infarction, hypertension, arrhythmias, and cardiomyopathy, denoting its translational potential as an intervention target." (PMID 37743632, 2023).
nasopharyngeal carcinoma (1 paper, 2024). A carcinoma arising from the nasopharyngeal epithelium. "Furthermore, the Epstein-Barr Virus (EBV) was found to inhibit RND3 expression, promoting nasopharyngeal carcinoma metastasis." (PMID 39719443, 2024).
plasmacytoma (1 paper, 2016). Plasmacytoma is a localized mass of neoplastic monoclonal plasma cells that represents approximately 5% of all plasma cell neoplasms. "EEF1A2 is a translation elongation factor gene that was previously shown to promote survival of mouse plasmacytoma cells, whereas EIF4E3, RND3/RhoE and FAM129A/Niban encode proteins that participate in various facets of cap-dependent translation initiation (described in more detail below)." (PMID 27626179, 2016).
prostate tumor (1 paper, 2023). "SPP1 and CLDN8 were upregulated in prostate tumor tissues, whereas COL4A6, RND3, DPT, EFS, and TGFB1I1 were downregulated." (PMID 37251946, 2023).
sarcoma (1 paper, 2010). A usually aggressive malignant neoplasm of the soft tissue or bone. "Very little is known about Rnd3 expression in human sarcomas." (PMID 21209796, 2010). "Thus, analysis of Rnd3 expression in human sarcomas might give information on the mechanism of invasion adopted by the tumor cells and help orientate the therapeutic strategy." (PMID 21209796, 2010). "We show here that Rnd3 (also known as RhoE), a cellular inhibitor of ROCK-I, plays a relevant role in regulating invasion and metastasis formation of sarcoma cells." (PMID 21209796, 2010). "In conclusion, the results presented here do suggest that sarcoma cells can adopt a protease-independent/ROCK-dependent mechanism of invasion and indicate that the Rnd3 gene can play a role in regulating the invasiveness and metastatic capacity of mesenchymal tumor cells." (PMID 21209796, 2010). "In addition, they point to Rnd3 as a possible regulator of mesenchymal tumor cell invasion and to ROCK as a potential therapeutic target for sarcomas." (PMID 21209796, 2010).
schizophrenia (1 paper, 2013). A major psychotic disorder characterized by abnormalities in the perception or expression of reality. "ZFHX3, RND3, KLF5, ERBB4, EGR1 and APC genes are both schizophrenia candidate genes and tumor suppression genes." (PMID 24564241, 2013).
tumor (56 papers, 2010 to 2025). "Rnd3/RhoE belongs to a family of genes, which encode small G proteins with important role in tumor initiation and progression." (PMID 38297314, 2024). "All these results suggest the association between the entotic events, loss of Rnd3 and tumor progression." (PMID 38218945, 2024). "RND3 protein expression levels are inversely associated with tumor size, tumor cell proliferation, and Notch activity, and positively correlated with patient survival time." (PMID 26108681, 2015). "Although the different expression pattern of Rnd3 was found in different tumors in human, Rnd3 expression was closely associated with tumor cell proliferation, cell migration/metastasis and diagnosis/prognosis." (PMID 25372032, 2014). "Our results indicate that reduced Rnd3 expression in tumor cells of mesenchymal origin can be linked to the acquisition of a ROCK-dependent mode of invasion and can increase the metastatic potential." (PMID 21209796, 2010). "All these results suggest a link between entotic events, Rnd3 loss and tumour progression." (PMID 38429285, 2024). "Although it appears that this protein is differently altered according to the tumour context, it has been demonstrated that aberrant RND3 expression may be the leading cause of tumour metastasis and chemotherapy resistance with a pro-tumourigenic role." (PMID 31623346, 2019). "We confirm that expression and genomic copy number of RND3 are predictive of clinical outcome, suggesting that changes in the activity of this particular Rho GTPase could be an early event associated to transformation and tumour expansion." (PMID 26132659, 2015). "MiR-17, another frequently reported oncomiR, promotes tumor cell growth and proliferation by suppressing the tumor-suppressor gene RND3." (PMID 40943532, 2025). "We noticed that the entotic cells are present in tumor sections with low expression of Rnd3 supporting our in vitro data concerning the implication of Rnd3 downregulation in the entosis process." (PMID 38218945, 2024). "We also assessed the SIRT7, EZH2, and RND3 protein levels in tumor tissues from each group of mice using IHC." (PMID 39719443, 2024). "Herein, RND3 inhibited the activity and clonogenic capacity of BCa cells, suggesting that its functions as a tumor suppressor in BCa." (PMID 39719443, 2024). "Previous studies have shown that BART2-5p can target and inhibit Rho family GTPase 3 and activate Rho signaling to enhance tumor cell motility." (PMID 37495108, 2023). "Another tumor suppressor that is downregulated early in the development of PCa, RND3, was expressed at significantly lower levels in the Methylation_H subtype than in the Methylation_H subtype." (PMID 33708770, 2021). "The genes repressed in both GE1-HCC and GE2-HCC included those with supposed tumour-inhibiting activity, e.g. CXCL14, CCBE1, IGFBP1, RND3, BMP10 and COLEC10, which encode proteins involved in extracellular matrix remodelling, migration and the immune response." (PMID 33541355, 2021). "miR-200b was found to be down-regulated in tumour budding cells at the invasive front in 71% of cases and is believed to have a tumour-promoting role in CRC by targeting RND3 and CDKN1B." (PMID 31623346, 2019). "RND3 is also known as RhoE, a GTPase that acts as a tumor suppressor, negatively regulating proliferation, migration and invasion." (PMID 31212604, 2019). "Most importantly, disease-free and overall survivals were significantly poorer for patients with Rnd3-positive tumours than for those with Rnd3-negative." (PMID 31623346, 2019).
tumor (continued). "We found that the percentage of apoptotic cells in tumours from cells overexpressing RND3 was significantly greater than that of the control group, and RND3 expression was positively correlated with apoptosis in human brain GBM samples." (PMID 31332862, 2019). "Significant increases in the expression level of cleaved caspase 3 and TUNEL‐positive cells were observed in GBM‐xenografted tumours overexpressing RND3 compared with the control group by immunoblot analyses (P < .05)." (PMID 31332862, 2019). "Significant increases in the expression levels of both E-cadherin and claudin were observed in the tumor developed from the RND3 stable expression U251 cells." (PMID 27705942, 2016). "Step 5- Development of data integration strategy: We developed a novel, multi-level data integration pipeline in order to shed light on the possible mechanisms of RND3 control of tumour function." (PMID 26132659, 2015). "The tumor size developed from the RND3 stable expression U251 cells was 4-folds smaller than the tumors developed from the GFP-tagged U251 cells." (PMID 26108681, 2015). "The levels of RND3 expression were inversely correlated with Notch activity, tumor size, and tumor cell proliferation, and positively correlated with patient survival time." (PMID 26108681, 2015). "With limited clinical epidemiology assessments, we found that the RND3 protein levels were closely correlated with GBM patient survival times, but inversely associated with patient tumor size and tumor cell proliferation." (PMID 26108681, 2015). "The results obtained were fully consistent with our predictions, suggesting that knock-down of RND3 induced an anti-tumour phenotype in U87 cells, which express high levels of RND3." (PMID 26132659, 2015). "The average tumor size was larger in patients with low expression of RND3 compared to the patients with high expression of RND3 although the tumor sizes were variable." (PMID 26108681, 2015). "Some of the pro-tumour effects of RND3 (migration and invasion) are likely to be a direct consequence of its known role in cytoskeleton remodelling." (PMID 26132659, 2015). "Taken together, this supports a critical role of RND3 in tumour expansion by modulating angiogenesis, cell migration, invasion, apoptosis and cell cycle dynamics." (PMID 26132659, 2015). "The mouse xenograft studies further indicated that ectopic expression of RND3 dramatically hindered the tumor growth." (PMID 26108681, 2015). "This suggests that Rnd3 inhibits cell-cycle progression of cortical progenitors, a result consistent with previous studies demonstrating a role for Rnd3 in fibroblast and tumor cell proliferation." (PMID 21435554, 2011). "Taken together, these results indicate a role for Rnd3 downregulation in promoting invasion and metastasis formation by mesenchymal tumor cells." (PMID 21209796, 2010). "Notably, under CDDP treatment, the combined application of the SIRT7 shRNA and EZH2 shRNA lentiviruses markedly enhanced the tumor RND3 protein levels compared to the administration of either shRNA lentivirus alone." (PMID 39719443, 2024). "Overexpression of RND3 in PCa cells can lead to cell growth arrest and death; conversely, its low expression can lead to ECM adhesion plaque loss, which increases the metastatic potential of tumor cells." (PMID 37251946, 2023). "In agreement with its cellular functions, a number of studies describing both a pro-tumorigenic and a tumour suppressor role have been reported, largely depending on tumour context, and several reports have described either Rnd3 upregulation or downregulation depending on the type of tumour." (PMID 36496976, 2022).